IFNG (interferon gamma)
Diseases named in the same sentence as IFNG in open-access papers (continued):
Sharing a sentence is not in itself a finding about the gene and the disease.
tumor (continued). "The early NK cell function recovery after autologous stem cell transplantation has been recently confirmed, showing the early recovery of NK cells were able to degranulate (CD107a expression) and produce interferon-gamma and macrophage inflammatory protein-1β upon tumor interaction." (PMID 36359863, 2022). "Hence, in vivo treatment with FAO inhibitor blocks T-cell proliferation and IFNγ production and thereby delays tumor growth." (PMID 35945203, 2022). "These accessory transgenes overcome the limitations of CAR T cell therapy by preventing checkpoint inhibition, supporting T cell function, promoting TH1 polarisation, and maintaining these populations in the presence of IFNγ, while combatting tumour heterogeneity by targeting additional TAA." (PMID 35205725, 2022). "IFNG has been shown to directly increase HLA-II expression in tumor cells." (PMID 35831288, 2022). "This pro-inflammatory environment could establish the perfect scenario for tumor eradication by different Ag-independent mechanisms mediated preferentially by IFNγ-producing TVM cells." (PMID 36330506, 2022). "Preliminary gene expression analysis comparing pre- and post- gendicine-treated HNC tumor revealed upregulation of IFNγ-signaling genes, decreased TGF-β and β-catenin signaling and increased CD8+ T cells signature, which is associated with increased clinical responses to ICIs." (PMID 35372020, 2022). "Although the IFNγ signaling pathway has been studied extensively, and different regulatory mechanisms have been uncovered, less is known about cell-intrinsic regulation of IFNγ-R1, its essential ligand-binding receptor chain residing at the tumor cell surface." (PMID 35395848, 2022). "Second, in a previous genome-wide loss-of-function screen for IFNγ signaling-independent tumor immune sensitizers, STUB1 was not identified as a hit19, highlighting its specific role as modulator of IFNγ signaling." (PMID 35395848, 2022). "Interestingly, other than the expected associations with tumour type and MSI status, the only significant predictor of IFNγ response were JAK1 LOF mutations, which predicted substantially reduced activity (β = −0.72, p = 2.48e‐07)." (PMID 35262923, 2022). "The A. pullulans-derived β-glucan could exhibit an anti-tumor activity by enhancing the interferon-gamma (IFN-γ) production and the NK cell activity by triggering the intestinal immunity." (PMID 35295918, 2022). "Recently the intrinsic role of PD-L1 and interferon gamma (IFNγ) signaling have been studied in several types of tumor cells, yet it remains unclear how they affect the metabolism and signaling pathways of ccRCC." (PMID 35656514, 2022). "Considering that interferon gamma, as the only type II interferon, has significant antiviral and antitumor properties and shows fewer side effects, we focused on the relationship between genes in the interferon gamma molecular tags and tumor progression and purity." (PMID 35865015, 2022). "Another possibility by which CD4+ T cell-derived IFNγ might inhibit tumor growth is by acting directly on endothelial cells." (PMID 36159781, 2022). "This interaction plays an important role in the IFNγ-dependent tumor surveillance system." (PMID 35456913, 2022). "For instance, IFNγ, together with TNFα, could induce PANoptosis in diverse cancer cell lines and reduced tumor size in an immunodeficient mice model." (PMID 35432318, 2022). "Furthermore, IFNγ secreted by tumor-infiltrating lymphocyte (TIL) is critical for M1 TAMs polarization." (PMID 36035994, 2022). "An A2AR antagonist, AZD4635 could prompt T cell proliferation and interferon gamma production and reduce the tumor load in multiple myeloma (MM) models." (PMID 35477416, 2022). "Various biomarkers such as PD-L1 expression, tumour mutation burden (TMB), microsatellite instability, microbiome, hypoxia, interferon-gamma (IFN-γ), and extracellular matrix have been reported on order to increase response to immunotherapy in patients, receiving ICIs." (PMID 35621637, 2022).
tumor (continued). "In most early studies, only the tumor-reactive cultures that detected interferon-gamma (IFN-γ) in co-culture with autologous tumor materials or tumor cells in vitro could be pre-selected for further outgrowth." (PMID 36077696, 2022). "One possible reason is that the induction of interferon gamma secretion by activation of toll-like receptor 4 occurs through the same pathway as the upregulation of CD155 expression during the activation process of T cells in the tumor immune microenvironment." (PMID 35326727, 2022). "Tumour organoids were pre-stimulated with IFNγ to enhance antigen presentation." (PMID 36237445, 2022). "Also, tumor IFNG signaling blocking improves ICB response by CD8+ T cell and NK/ILC1-mediated killing." (PMID 35419410, 2022). "The IFNγ could then stimulate an anti-angiogenic effect along with the induction of adhesion molecules that permit the entry of T cells into the tumor islet." (PMID 36330506, 2022). "Subsequently, cytokine secreted from T cells in response to those tumor cells was increased, and those cytokines including IL‐2, IL‐7, IL‐15, and interferon gamma (IFN‐g), could induce PD‐L1 expression." (PMID 34907653, 2022). "There was a ~ three-fold increase in IFNγ secretion, a marker of tumor-specific T cell priming and activity, when splenocytes collected from the cured mice were stimulated by the two KRAS-mutant tumor cell lines, but no IFNγ induction was observed in the non-KRAS-mutant cell line." (PMID 35045886, 2022). "When inflammatory substances like interferon-gamma and lipopolysaccharide excite monocytes, they activate M1 macrophages, which can emit inflammatory factors like IL-6 and tumor necrosis factor-alpha and phagocytize invading infections and tumor cells." (PMID 36589842, 2022). "NK cells might limit tumor metastasis by activating NKp46 in the intratumoral NK cells secreting interferon-gamma, and interferon-gamma increases the expression of extracellular matrix protein fibronectin 1, affecting the primary tumor architecture." (PMID 36359863, 2022). "The antitumorigenic immune components of tumor microenvironment are natural killer (NK) cells, dendritic cells (DC), cytotoxic T lymphocytes (CTLs), and M1 tumor-associated macrophages (M1 TAMS) secreting mainly proinflammatory cytokines like IL-1β, IL-1α, IL-6, IFNγ, TNFα etc.." (PMID 36496977, 2022). "However, after TIL injection, the tumor became very strongly positive for PD-L1 as assessed by immunohistochemistry, suggesting that the TILs had been activated to secrete interferon gamma." (PMID 39131259, 2022). "Silencing of PD-L1 significantly suppressed inflammatory pathways upregulated by IFNγ, suggesting that targeting PD-L1 could enhance tumor suppression in ccRCC." (PMID 35656514, 2022). "Nevertheless, the infiltrating CD8+ T cells could maintain their functionality because it was proven that the increased levels of IFNγ in tumor tissue of patients with favorable clinical outcomes are maintained." (PMID 36142615, 2022). "Recent findings show that interferon-gamma produced by CD8 T cells has a tumor-suppressing impact when ferroptosis is activated, suggesting that the immune system may help to prevent carcinogenesis through ferroptosis." (PMID 35774794, 2022). "In addition, this process is dependent on the tumor cell–intrinsic ability to respond to IFNγ, which is regulated by KRAS signaling and contributes to long-term therapeutic efficacy of KRASG12C inhibition." (PMID 35857848, 2022). "Furthermore, we showed that both tumor proliferation and interferon-gamma response scores were significantly higher in the HER2 mutation subgroup than in the HER2 wide-type subgroup in the TCGA Pan-Cancer cohort." (PMID 35281032, 2022). "In lung, prostate, renal, breast, endometrial, and pancreatic cancer cells, low doses of IFNγ in the tumor microenvironment, generated by host immune cells or during cytokine therapy, may in fact favor tumor progression." (PMID 35806366, 2022).
tumor (continued). "The TME delivery of IFNγ inhibited tumor growth and angiogenesis by triggering the immune response." (PMID 36679900, 2022). "Finally, IFNγ directly acts on endothelial cells to stop blood flow in vascularized tumors leading to tumor collapse." (PMID 35163755, 2022). "The presence of IFNγ in the TME has been linked to upregulation of MHC I and antigen-processing molecules, with antiproliferative and antiangiogenetic effects accompanied by effector T-cell recruitment to the tumor side." (PMID 35892641, 2022). "Nevertheless, studies revealed that IFNG promotes tumor immune evasion by upregulating PD-L1 in a JAK-STAT pathway-dependent manner, implying that tumors characterized by increased IFNG response may be sensitive to immune checkpoint blockade therapy." (PMID 35492352, 2022). "IFNγ and TNFα can co-induce dormancy in tumor cells to promote carcinogenesis." (PMID 35582541, 2022). "Innate and adaptive immune cells such as activated cytotoxic CD8+ T lymphocytes cells and natural killer cells produce interferon gamma (IFNγ) in the tumor microenvironment, which in turn induces the expression of the programmed death ligand 1 (PD-L1 or B7-H1) on tumor cells." (PMID 35656514, 2022). "It was next evaluated whether the T cell response induced by organoid co-culture was tumour-specific or should be considered an artefact of IFNγ treatment or organoid culture." (PMID 36237445, 2022). "In addition to their cytotoxic function, they secrete the major stimulatory cytokine interferon gamma (IFNγ) to induce and maintain interferon-induced anti-tumor immunity." (PMID 33603130, 2022). "Thus, anti-tumor immunity and therapeutic responses to immune oncology agents are critically determined by tumor cell intrinsic IFNγ signaling." (PMID 35902886, 2022). "Besides, other studies have shown that cryoablation reduces tumor metastasis and that the T lymphocyte in tumor-draining lymph nodes (TDLN) secrete higher levels of interferon-gamma (IFN-γ) than surgery." (PMID 36119081, 2022). "Furthermore, we were unable to detect antigen-specificCD8+ T cells against predicted clonal neoantigens when pulsingsplenocytes isolated from KPAR1.3 tumour-bearing mice in an IFNγ enzyme-linkedimmune absorbent spot (ELISpot) assay (SupplementaryTable S1)." (PMID 35930804, 2022). "It is well known that extrinsic IFNγ can up-regulate the expression of PD-L1 in tumor cells." (PMID 35107757, 2022). "In particular, TGFβ has been demonstrated to induce a pro-tumor state characterized by high expression of arginase and strong immunosuppressive activity; on the other hand, IFNβ, IFNγ and GM-CSF stimulate TANs’ polarization into an anti-tumor phenotype characterized by high cytotoxic activity." (PMID 35158779, 2022). "Similarly, in the orthotopic Hepa1-6 HCC mouse model splenectomy effectively reduced the suppressive activity of neutrophils and increased the frequency of tumor-infiltrating IFNγ+ CD8 T cells." (PMID 36561751, 2022). "Additionally, vanadate/VSVΔ51 combination treatment led to an enhancement in T cell recruitment to tumor sites with significantly increased interferon-gamma (IFN-γ) producing CD8+ T cells, particularly in treatment-responsive animals." (PMID 36532027, 2022). "C1QC+ tumor-associated macrophages and INHBA+ monocytes showed a significant reduction in inflammation-related pathways, including the interferon alpha pathway, IL-6 pathway, and interferon gamma pathway." (PMID 36052088, 2022). "Despite the differential composition of g1 ILCs in the different tumor stages, all intratumoral g1 ILCs produced lower levels of IFNγ and presented increased expression of the exhaustion markers Tigit, Pdcd1 (PD1), and Lag-3, the latter two being the most prominent in ILC1s." (PMID 36372017, 2022). "Canonically, IFNγ secreted by T cells induces PD-L1 expression in multiple tumor types." (PMID 35631400, 2022).
tumor (continued). "Additionally, IFNγ has been reported to enhance the expression of major histocompatibility class 1 molecules and promote the presentation of tumor-specific antigens." (PMID 35053427, 2022). "In cancer literature, IFNγ induction and IL-10 suppression in Treg appears to be an early requirement for Treg to properly mediate an anti-tumor environment, clear more tolerant Treg from their surroundings and boost anti-tumor immunity." (PMID 36558773, 2022). "Existing studies have confirmed that the STAT3-mediated inhibitory tumor immune response pathway has an antagonistic effect on the STAT1-driven antitumor immune response, which may lead to the loss of IFNγ/JAK/STAT1 pathway function." (PMID 36185620, 2022). "Furthermore, the addition of TLR7 agonists progressed the proportion of M1 to M2 tumor-associated macrophages (TAMs) and promoted the infiltration of tumor-specific IFNγ -producing CD8+ T cells." (PMID 35745800, 2022). "IFNγ levels in tumor tissue extract from L/L mice were significantly higher than those in WT mice." (PMID 36224346, 2022). "Indeed, this pectin prevents glycosylated cytokines (IFNγ between others) be captured by galectin-3 and therefore allowing the chemokine gradient needed to attract lymphocytes towards the tumor." (PMID 36703969, 2022). "ILC1s depend on T-bet for their development, can produce IFNγ, and may function in tumor immune surveillance and clearance." (PMID 34385592, 2022). "In some cancer models, CD40-mediated activation of macrophages, which possibly mimics the effects of CD4+ T cell stimulation, has been shown to drive tumor control in an IFNγ-dependent manner, resulting in substantial remodeling and collapse of the tumor’s fibrotic network." (PMID 34282297, 2022). "In Tumor Microenvironment, a major source of IFNγ are T cells." (PMID 35440133, 2022). "In addition to improved tumour infiltration, o9R pmel T cells showed a higher in vitro cytolytic capacity and increased production of IFNγ compared to their o2R counterparts." (PMID 35676488, 2022). "Differences in gene expression between tumours growing in immunocompetent and immunodeficient hosts were related to changes in the expression of extracellular matrix proteins and changes in interferon gamma and Il-2 signaling, consistent with the differences in T-cell abundance (PC2)." (PMID 36525288, 2022). "Conversely, TGFβ/IFNγ-producing CD4 T cells are the main components of pro-tumor immune reactions." (PMID 36289759, 2022). "Preclinical studies using murine tumor models have indicated an increase in the number of activated dendritic cells (APCs) as evidenced by increased expression of MHC class II, CD80, and CD86, as well as increased levels of IL-12 and IFNγ in the tumor microenvironment post HIFU." (PMID 35848421, 2022). "Notably, IFNγ is one of the players that induces tumor cell death, including apoptosis, necroptosis, and ferroptosis." (PMID 34385592, 2022). "The most essential cytokines in the anti-tumour response are IL-12, granulocyte-macrophage colony-stimulating factor GM-CSF, T cell growth factor IL-2, IL-2-related cytokines IL-15 and IL-21 and pro-inflammatory IFNγ and TNFα." (PMID 36140243, 2022). "Thus, NK cells eliminate tumour cells by triggering an antibody-dependent cell-mediated cytotoxic response and activate other leukocytes using IFNγ." (PMID 36267157, 2022). "On the other hand, tumor cells may also increase immunosuppressive signals under the pro-apoptotic stimulation of IFNG, thereby inhibiting the survival of T cells and promoting the infiltration of immunosuppressive immune cells." (PMID 35692844, 2022). "Interestingly, in the high ADO score group, the expression level of immune effector molecule IFNG decreased significantly, while the level of NK cells, a main member of tumor killing cells, was relatively high." (PMID 36518306, 2022).
tumor (continued). "Interestingly, α1 demonstrated significant changes already at an early stage of tumor development (“Small tumor” group), which correlates with flow cytometry data on IFNγ production and the expression of CD25 and CD69." (PMID 36555468, 2022). "Current studies have confirmed that STAT3-mediated inhibitory tumor immune response has an antagonistic effect on STAT1-driven antitumor immune response, which may lead to the loss of function of the IFNγ/JAK/STAT1 pathway." (PMID 36185620, 2022). "Tumor NK cells expressed similar DEGs to tumor T cells and were enriched for genes associated with protein folding and cytokine expression, including genes coding for heat shock proteins HSPA6, HSPA1B, and HSPA1A, and IFNG, a common cytotoxic marker." (PMID 35534852, 2022). "Furthermore, NK cells secrete interferon-gamma (IFN-γ), which causes the recruitment of other immune effectors such as macrophages and dendritic cells to carry out alternative anti-tumour activities." (PMID 35453554, 2022). "In this context we speculated that IFNγ produced by CD8+ T cells could be responsible for this early antitumor effect, especially since previous reports have demonstrated that IFNγ participates in different stages of tumor growth control." (PMID 36330506, 2022). "Moreover, these Vγ2Vδ2 T cells activated jointly by Vγ2 x PD-L1 and PD-L1 tumor cells displayed multifunctional effector phenotypes, which co-expressed IFNγ, TNFα, and CD107a." (PMID 35784353, 2022). "It has been demonstrated that MDSCs-derived exosomes contain matrix metalloproteinases (MMPs) and different cytokines, chemokines, and growth factors (CSF, VEGF, MCP, SDF1α, TNFα, and IFNγ), which establish a pro-metastatic microenvironment that allows the metastatic progression of tumor cells." (PMID 35757002, 2022). "From a therapeutic point of view this could be beneficial, because several IFNγ target genes, such as HLA, contribute to tumor eradication." (PMID 35395848, 2022). "Prolonged exposure of tumor cells to IFNγ is crucial for an antitumoral effect." (PMID 35806366, 2022). "Interferon gamma also plays a dual tumor-suppressor and protumorigenic roles in cancer." (PMID 36500393, 2022). "Mature DCs enriched in immunoregulatory molecules (mregDCs), co-expressing immunoregulatory genes (Cd274, Pdcd1lg2, and Cd200) and maturation genes (Cd40, Ccr7, and Il12b), can uptake tumor antigens, upregulate IL-12 in an IFNγ-dependent manner, and initiate effector T cells response." (PMID 36244976, 2022). "Because IFNγ, produced in response to T-cell activation, can modulate distant tumor cells —including tumor cells more than 800 μm away —IFNγ is likely to play a crucial role in Fas-mediated kill of tumor cells." (PMID 36271507, 2022). "Furthermore, the potential antitumor activity of the cryopreserved NK cells was confirmed by comparable ability to kill various tumor cell lines and similar levels of IFNγ, TNFα, and CD107a produced after stimulation with cytokines and/or K562 cells." (PMID 35464440, 2022). "Additionally, tumor-specific MHC-II expression is correlated with the activation of IFNG pathway, higher levels of Th1 cytokines, and CD4+/CD8+ lymphocytes infiltration." (PMID 35350568, 2022). "As well, increased IFNγ secretion suppresses Tregs in the tumor microenvironment." (PMID 35515137, 2022). "These cells may be responsible for reduced T cell infiltration in Tyk2ΔIEC tumors and allow tumor growth despite enhanced IFNγ signaling and intact immune surveillance." (PMID 36185806, 2022). "GO analysis based on DEGs of NK-FCGR3A-CCL3 across MM patients indicated that NK-FCGR3A-CCL3 from high tumor infiltration group displayed impaired “interferon-gamma mediated signaling pathway”, “cellular response to decreased oxygen levels” and “positive regulation of mitochondrion organization”." (PMID 36532059, 2022). "Thus, epigenetic regulation of the IFNγ signaling pathway can affect tumor immunity and immunotherapy." (PMID 34385592, 2022).